EGFR (epidermal growth factor receptor)
Diseases named in the same sentence as EGFR in open-access papers (continued):
Sharing a sentence is not in itself a finding about the gene and the disease.
glioblastoma (continued). "CNTN2 has been shown to promote glioma stem-like cell proliferation through regulation of EGFR-, HES1-, and APP/AICD-associated signaling pathways, and its knockdown suppresses tumor cell growth in vitro, supporting a functional role in glioblastoma progression." (PMID 41596752, 2026). "Interestingly, erlotinib in combination with the chemotherapeutic agent gemcitabine showed efficacy in a patient with a pancreatic ductal adenocarcinoma carrying the EGFR:c.2189T>G p.(L730R) GV that was also detected in a glioblastoma patient here." (PMID 41546701, 2026). "The most common in glioblastoma is genomic amplification, which leads to overexpression of EGFR." (PMID 39796751, 2025). "Importantly, recent studies have demonstrated that circ-EGFR deprivation suppresses tumorigenicity in brain tumor cells and enhances the efficacy of nimotuzumab in glioblastoma." (PMID 41214390, 2025). "Combination therapy of EGFR-amplified glioblastomas is, therefore, a possibility that would allow the treatment of a large proportion of patients, as they account for 40–60% of all glioblastoma patients." (PMID 40075591, 2025). "Given that Oxamate suppressed EGFR expression and activity, we next investigated whether Oxamate enhances radiosensitivity in glioblastoma cells." (PMID 40565174, 2025). "Currently, it is unclear why EGFR-targeted therapies are ineffective in glioblastoma." (PMID 39796751, 2025). "Similarly, in glioblastoma cells, activated EGFR directly phosphorylates PFKP, leading to PI3K activation, PFK2 phosphorylation, and increased PFK1 activity." (PMID 39433211, 2025). "In the remaining cases, information on CDKN2A/B status was missing in 40 patients with IDH-mutant astrocytoma, and information on molecular features of glioblastoma (TERT mutation, EGFR amplification, 7p + /10q-) was missing in 27 patients with IDH-wildtype glioma." (PMID 39954095, 2025). "The results revealed that EGFR was related to glioblastoma with the highest score after PTEN." (PMID 39888904, 2025). "The cell SELEX method (Cell-SELEX Aptamer for Highly Specific Radionuclide Molecular Imaging of Glioblastoma In Vivo) was used to search for DNA oligonucleotides that could bind EGFR and EGFRvIII on the cell surface of the U87MG cell line." (PMID 39940838, 2025). "For example, the glioblastoma natural circEGFR utilises an iORF through rolling translation to generate repeating amino acid sequences, rolling‐translated EGFR, reinforcing EGFR membrane localisation and promoting tumourigenicity in brain tumour‐initiating cells." (PMID 41284375, 2025). "Our study shows that alterations in EGFR, one of the most common pathways in glioblastoma, may be a driver of REP." (PMID 41212363, 2025). "We categorized nine glioblastoma cell lines into four groups based on the expression levels of EGFR and MIG6: (a) EGFR‐positive (EGFR+) and MIG6‐high level (MIG6high); (b) EGFR+ and MIG6‐medium level (MIG6medium); (c) EGFR+ and MIG6‐low level (MIG6low); (d) EGFR‐negative (EGFR−) and MIG6low." (PMID 39129344, 2025). "Furthermore, the expression of EGFR in glioblastoma cells was down-regulated by plinabulin treatment." (PMID 39877641, 2025). "The latest WHO classification adopts a multi-layer integrated approach to defining glioblastoma, integrating histological features with molecular signatures: IDH-1 mutation, EGFR amplification, TERT promoter mutations, and the combined gain of chromosome 7 and loss of chromosome 10." (PMID 41008823, 2025). "The EGFR is frequently mutated in cancer, with exon 19 deletions and the exon 21 L858R point mutation commonly associated with NSCLC, while the EGFRvIII variant is a prevalent driver of glioblastomas." (PMID 39433211, 2025).
glioblastoma (continued). "IDH-wildtype glioblastomas typically occur in older adults, exhibit aggressive biological behavior, and frequently harbor genetic alterations, such as TERT promoter (TERTp) mutations and epidermal growth factor receptor (EGFR) amplification." (PMID 41473634, 2025). "An altered IR cellular trafficking like that observed for EGFR in C3G-silenced glioblastoma cells could also explain it." (PMID 41057310, 2025). "However, an early phase I clinical trial for recurrent glioblastoma saw success in CAR T cells engineered to target both EGFR III and wildtype EGFR9." (PMID 40730675, 2025). "Our findings suggest that the combination of catalytic LSD1 inhibitors and EGFR inhibitors could be a promising therapeutic strategy and warrants continued evaluation in glioblastoma models." (PMID 41497449, 2025). "Notably, one study blocked EGFR signaling by targeting C-E-Cad, enhancing anti-EGFR therapy, and inhibiting the tumorigenicity of glioblastoma stem cells." (PMID 40034125, 2025). "For instance, glioblastomas with EGFR amplification may be sensitive to EGFR inhibitors, and tumors that are BRAF mutant-dependent can be treated with BRAF/MEK inhibitors." (PMID 40806492, 2025). "Similarly, Oncostatin M receptor (gene: OSMR), a member of the type I cytokine receptor family, functions as a co-receptor for EGFR and enhanced EGFR signaling in glioblastoma." (PMID 39995668, 2025). "EGFR, NF1, and PDGFRA mutations are more frequent in glioblastoma." (PMID 40564017, 2025). "Interestingly, a very recent phase 1 clinical study confirms that EGFR is a suitable immunotherapeutic target in glioblastoma." (PMID 40075591, 2025). "Clinically, our findings suggest that glioblastoma patients with EGFR alterations may benefit from expedited initiation of adjuvant therapies after surgery to mitigate the risk of rapid tumor progression." (PMID 41212363, 2025). "Furthermore, EGFR gene rearrangement has been shown in a majority of glioblastoma cases (70–90%) with EGFR overexpression." (PMID 40362634, 2025). "EGFR and its mutant isoform EGFRvIII are key drivers in glioblastoma." (PMID 40624498, 2025). "For instance, EGFR is a tyrosine kinase receptor altered in 40–45% cases of glioblastoma." (PMID 41212363, 2025). "In addition, while fluorescently tagged anti-EGFR antibodies have been in other studies to guide oncologic surgery in colon cancer, pancreatic cancer, and glioblastoma, these studies lack the power to determine optimal dosing for HNC studies." (PMID 40380992, 2025). "Interestingly, local administration of EGFRvIII-targeting CAR-T cells that simultaneously secrete TCEs against wild-type EGFR, achieved radiographic tumor regression in patients with glioblastoma, and demonstrated a safe profile." (PMID 41341587, 2025). "EGFR dysregulation is one of the most common mechanisms in glioblastoma pathogenesis." (PMID 39129344, 2025). "The latest 5th edition recently refined the diagnosis of glioblastoma by adopting a multi-layered integrated approach incorporating new molecular criteria such as TERT promoter mutation, EGFR amplification or chromosomal 7 + gain / chromosomal 10- loss for IDH-1 wildtype tumors." (PMID 40067514, 2025).
glioblastoma (continued). "Furthermore, we established an eight‐marker glioblastoma risk signature (GBRS) using scRNA‐seq and eQTL data, with higher GBRS scores observed in the NFkB cluster and EGFR cluster, indicating their highlighted aggression among malignant cells." (PMID 40760788, 2025). "Further, studies of [111In]In-DOTA-panitumumab-AuNPs showed selective binding to the cell surface and internalization into the cytoplasm and nucleus for EGFR-overexpressing U251-Luc cells compared to U87MG cells with low EGFR or or murine GL261 glioblastoma cells with negligible EGFR." (PMID 40676315, 2025). "Larger sample sizes could both confirm our findings and allow for further conclusions regarding specific EGFR alterations in early glioblastoma progression." (PMID 41212363, 2025). "EGFR amplification is the most common alteration in primary glioblastoma." (PMID 40075591, 2025). "In glioblastoma, EGFR p.T363I has been reported in cases of glioblastoma in a single tumor sector." (PMID 40724977, 2025). "This study identifies EGFR alterations as a significant predictor of REP in glioblastoma." (PMID 41212363, 2025). "EGFR is overexpressed in ~60% of primary glioblastoma and 10% of secondary glioblastomas." (PMID 41208963, 2025). "The combined effects of erlotinib and investigational HDAC inhibitor, scriptaid, increased H3K9 acetylation and could overcome erlotinib resistance and re-sensitize glioblastoma cells to EGFR inhibition." (PMID 38183103, 2024). "In addition to its function as a potential predictive biomarker, EGFR gene amplification is also used for glioblastoma classification." (PMID 38674436, 2024). "Furthermore, PLD can repress glioblastoma cell migration and invasiveness by inhibiting the EGFR/AKT/ERK1/2/STAT3/SOX2/Snail signaling pathway." (PMID 39408901, 2024). "Future combination studies could include EGFR inhibitors with high penetrance across the BBB as well as a focus on the development of EGFR inhibitors selective for the mutant EGFR in glioblastoma, EGFRvIII." (PMID 38183103, 2024). "Nevertheless, melanoma and glioblastoma share only two overlapping targets (EGFR and MMP2)." (PMID 39628999, 2024). "Recent preclinical studies utilizing in vitro glioblastoma stem cells (GCS) models and GB orthotopic xenograft model with EGFR variant III showed antitumor activity along with inhibition of EGFR downstream signaling pathway for the third-generation EGFR inhibitor osimertinib." (PMID 39439947, 2024). "It is thus appropriate for our study, since 76% of glioblastomas are positive for EGFR-neu, whereas normal tissue expresses little if any EGFR-neu, together with the fact that Lindberg and colleagues used Oli-neu cells to demonstrate that OPCs can act as cells of origin for experimental glioma." (PMID 38994940, 2024). "Moreover, Fyn and c-Src are effectors of oncogenic EGFR signalling in glioblastoma and enhance invasion and tumour cell survival in vivo." (PMID 39697541, 2024). "In addition, EGFRvIII is known to activate the NF-κB signalling pathway via RIPK1-ubiquitination, while WT EGFR seems to suppress this process leading to RIPK1-dependent apoptosis in glioblastoma." (PMID 38789573, 2024). "EGFR is a target of therapeutics in cancers besides glioblastoma." (PMID 38396993, 2024). "Since glioblastoma activates the EGFR signalling pathway along with Fyn and Src, blocking Fyn and Src may increase the effectiveness of anti-EGFR-targeted therapy." (PMID 39697541, 2024). "Summary of EGFRVIII and EGFR CAR T cell studies in glioblastoma." (PMID 39364321, 2024). "Moreover, extrachromosomal mutant epidermal growth factor receptor (EGFR) DNA contributes to EGFR-tyrosine kinase inhibitor (TKI) resistance in glioblastoma." (PMID 38439082, 2024).
glioblastoma (continued). "Interestingly, EGFR targeting appears to be able to overcome, at least partially, the acquired resistance of glioblastoma xenografts to inhibition of VEGF-driven angiogenesis." (PMID 38570528, 2024). "Furthermore, EGFR expression is upregulated in primary glioblastoma multiforme, and it correlates with tumor malignancy." (PMID 38473403, 2024). "In glioblastoma, EGFR and PDGFRA amplification are responsible for extrachromosomal mutations." (PMID 39202666, 2024). "In a different trial, glioblastoma patients received CART-EGFR-IL13Rα2 cells targeting both EGFR and IL13Rα2 intrathecally through an intraventricular reservoir, leading to a transient regression of the tumor in all patients and early persistence of CAR T cells in the CSF." (PMID 39199630, 2024). "Among the most frequently mutated genes in adult glioblastomas, no EGFR, PTEN, or RB1 alterations were reported among the most frequently mutated genes in CMMRD-associated gliomas." (PMID 39233831, 2024). "Additionally, depatuxizumab mafodotin (ABT-414), a monoclonal antibody-drug combination, inhibits EGFR amplification in glioblastoma and blocks tubulin polymerization through the tubulin inhibitor monomethyl auristatin F, further combating the tumor." (PMID 38686058, 2024). "The upregulation of the EGFR gene is predominantly detected in cases of glioblastoma." (PMID 39407193, 2024). "The finding that EGFR amplification in and of itself has the highest specificity for glioblastoma lends additional support to the need to determine specific cutoffs when using FISH to establish the presence of an EGFR amplification versus a chromosome 7 polysomy without EGFR amplification." (PMID 38605523, 2024). "An oHSV engineered to express EGFR antibody cetuximab linked to the chemotactic chemokine CCL5 enhanced chemotactic and activation immune cells, inhibited tumor EGFR signaling, reduced tumor size and prolonged survival in glioblastoma-bearing mouse models." (PMID 39518074, 2024). "Similarly, intrathecal bivalent CAR-T cells targeting EGFR and IL13Rα2 in recurrent glioblastomas reported interim results showing manageable toxicity and encouraging progression-free survival." (PMID 38892305, 2024). "Clinical trials evaluating traditional EGFR inhibitors in glioblastoma have shown variable results." (PMID 38396993, 2024). "Interestingly, a cross-talk between the AR and epidermal growth factor receptor (EGFR) pathways has been described in glioblastoma cells and AR activation in vitro regulates transcription programs related to radiation-induced DNA damage repair." (PMID 38233838, 2024). "Additionally, the identification of IDH mutations has been leveraged to guide prognosis, while the definition of glioblastoma has been refined through the analysis of TERT promoter, EGFR amplification, gain of chromosome 7, and loss of chromosome 10." (PMID 38553633, 2024). "EGFR amplification is found in approximately 40–50% of glioblastoma cases." (PMID 39772250, 2024). "Interestingly, epidermal growth factor receptor (EGFR) inhibition in human glioblastoma cells results in a reduction of telomerase activity and telomere shortening and is associated with slower tumor progression in mice in a dose-dependent manner." (PMID 38240992, 2024). "The ANXA1 substrate EGFR was also found to have high expression in primary glioblastomas." (PMID 38639785, 2024). "Additionally, deletion of exons 2–7 in the EGFR extracellular domain (ECD) results in a constitutively active “EGFRvIII” mutant frequently observed in glioblastoma multiforme (GBM)." (PMID 39065587, 2024). "Monoclonal antibodies may prove to be a useful therapeutic if designed to properly target EGFR in glioblastoma." (PMID 38396993, 2024).
glioblastoma (continued). "The relevance of EGFR mutations in glioblastoma is strong, but despite therapeutic potential, no single targeted therapy against EGFR or its variants has been proven to improve survival in glioblastoma patients." (PMID 39518074, 2024). "First, the cytotoxic activity of NKAR-NK-92 and NKAR_RD-IL15-NK-92 cells against homogeneous cultures of GL261/EGFR, GL261/ErbB2, and GL261/ErbB2/EGFR glioblastoma cells in the presence of NKAB-EGFR or NKAB-ErbB2, or a combination of both molecules, was tested." (PMID 38334638, 2024). "Notable pathways included MAPK signaling, cancer pathways, EGF/EGFR signaling, Glioblastoma signaling, Ras signaling, EGFR tyrosine kinase inhibitor resistance, miRs in cancer, PI3K-AKT signaling, p38 MAPK signaling, glioma, miRs in cardiomyocyte hypertrophy, and mTOR signaling." (PMID 39348350, 2024). "It was shown that high exosome-transferred miR-1238 level in TMZ-resistant glioblastoma cells could confer TMZ resistance by directly targeting the CAV1/EGFR pathway." (PMID 38379858, 2024). "The findings suggest that the activation of the epidermal growth factor receptor (EGFR) contributes to YTHDF2 overexpression in glioblastoma, thereby linking EGFR signaling, a pivotal factor in the progression and resistance to therapy of glioma, to m6A-dependent mRNA modification." (PMID 38398118, 2024). "EGFR/EGFRvIII downstream signaling includes constitutive activation of PIP3K/Akt, RAS/MAPK, and Bcl-Xl and has been implicated in glioblastoma cell proliferation, inhibiting apoptosis and enhancing glioblastoma invasiveness." (PMID 38928445, 2024). "Like GC1118, the use of other anti-EGFR antibodies in glioblastoma has been elucidating." (PMID 38396993, 2024). "In addition, CAR T cells that secreted EGFR-specific bi specific T cell engagers (BiTEs) for patients with glioblastoma were designed." (PMID 39835140, 2024). "Sixty-three percent of the patients could be conclusively reclassified as glioblastoma based on either TERT mutation, EGFR amplification, or both." (PMID 38672254, 2024). "In glioblastoma, coadministration of EGFR inhibitors with other drugs may increase therapeutic vulnerability of the tumor and suppression of downstream growth pathways." (PMID 38396993, 2024). "The PI3K/Akt/mTOR signaling cascade, a critical component of the upstream autophagy pathway, is commonly dysregulated and is observed in 90% of glioblastoma (GBM) cases, and is caused by the overexpression of upstream activators, like epidermal growth factor receptor (EGFR)." (PMID 39348350, 2024). "Moreover, the analysis of DNA copy number variation of 543 glioblastoma samples shed light on some common amplification events on chromosome 7 (EGFR, MET, CDK6), chromosome 12 (CDK4 and MDM2), and chromosome 4 (PDGFRA)." (PMID 39148319, 2024). "Similarly, in vivo studies using glioblastoma xenografts in mice, showed slowed growth and increased apoptosis when EGFR expression was suppressed using a tetracycline-regulatable expression system." (PMID 38396993, 2024). "Furthermore, DYRK1A expression positively correlates with EGFR levels, and DYRK1A inhibitors reduce EGFR-dependent glioblastoma growth." (PMID 39436397, 2024). "Additionally, basic fibroblast growth factor receptor (BAFR) and epidermal growth factor receptor (EGFR), which are common molecular markers for glioblastoma, were selected as diagnostic factors for graphing." (PMID 39771050, 2024). "In contrast, poor-prognosis low-grade gliomas (lacking IDH mutation) and primary glioblastomas (GBMs) are characterized by EGFR amplification along with deletions/mutations of the phosphatase and tensin homolog tumor suppressor gene (PTEN)." (PMID 38254732, 2024). "In glioblastoma, EGFR displays the highest enrichment of any gene." (PMID 38396993, 2024).